INS (insulin)
Diseases named in the same sentence as INS in open-access papers (continued):
Sharing a sentence is not in itself a finding about the gene and the disease.
diabetes (continued). "Patients with APS-3 showed higher age (p = 0.001), age of onset of diabetes (p = 0.006), VAI (p = 0.008) and TSH (p = 0.004) and lower total insulin as U/day (p < 0.001) and U/Kg (p = 0.001) and irisin (p = 0.002) compared to T1DM." (PMID 33099763, 2021). "In Nepals private sector, a lowest paid worker would spend between the range of 0.07 (aspirin) and over three days wages (insulin and benzathine-benzyl penicillin) to purchase a monthly supply of a given generic CVD/diabetes EM." (PMID 34040951, 2021). "Type 2 diabetes mellitus (T2DM) is a progressive disease characterized by continuing decline of pancreatic islet β-cell function and subsequent decrease in endogenous insulin secretion." (PMID 33602996, 2021). "Participants took the following medications for diabetes: Metformin (62.5%), Repaglinide (31.25%), DPP-4 inhibitor (31.25%), Sulfonylurea (18.75%), GLP -1 (6.25%), SGLT2i (6.25%), insulin (6.25%)." (PMID 34404385, 2021). "Diabetes mellitus (DM) is a metabolic disorder of multiple etiologies characterized by chronic hyperglycemia and abnormalities in carbohydrate, fat, and protein metabolism which result from irregularities in insulin secretion, insulin action, or both." (PMID 35432813, 2021). "This is consistent with our study, which showed patients who had diabetes for more than 5 years, more than 40% of moderate urban level, higher ratio of CKD, and slightly higher proportion of insulin use." (PMID 33478477, 2021). "We aimed to assess the impact of insulin pen devices with safety needles (SPN) on the usability, behavioral, lifestyle, and emotional aspects of type 1 diabetes mellitus (T1DM) in adolescents and young adults." (PMID 33927957, 2021). "Therefore, to analyze whether these effects were dependent on the action of insulin, here we used a model with markedly reduced insulin production, the Akita mouse, to examine the long-term effects of increasing liver glycogen on glucose metabolism, food intake, and diabetes complications." (PMID 33667544, 2021). "The insulin and HOMA-IR levels were more favorable in people with a high RMR, but the sleeping RMR was higher in 560 Pima Indians with diabetes and impaired glucose tolerance." (PMID 33540643, 2021). "One study revealed that SIRT5 is downregulated in the pancreas of mice suffering from type 2 diabetes mellitus (T2DM), and plays a role in maintaining β-cell mass and function in glucolipotoxic conditions, retaining insulin secretion." (PMID 33806509, 2021). "In fact, it has been reported that CLZ response and diabetes mellitus share genetic mechanisms, including recurrent genes such as CACNA1C in common pathways (e.g., insulin secretion)." (PMID 33557049, 2021). "Subsequently, the relationship between insulin treatment and weight gain in people in T1DM is probably bi-directional, and adds further challenges to the management of diabetes in this population." (PMID 34530819, 2021). "In a STZ-mediated diabetes model, pancreas-targeted CLU OE induced significantly higher GLU levels, as well as GLU, INS and PYR decreased tolerance indicating a more severe diabetic phenotype in those Tg animals." (PMID 33744871, 2021). "In both T1D and T2D, we found enrichment of monogenic forms of diabetes, as expected —2 genes in T1D (RASGRP1, INS) and 8 in T2D (HNF1B, GCK, WFS1, KCNJ11, ABCC8, HNF1A, PPARG, SLC2A2)." (PMID 33836063, 2021). "In this study, we first evaluated the ability of machine learning models to predict insulin initiation by specialists using the Japan Diabetes Clinical Data Management (JDDM) Study Group, which consists of diabetes specialists." (PMID 33502325, 2021). "Insulin and IGF-1 are neurotrophic for retinal neurons via activation of the Akt pathway, a pathway specifically impaired by diabetes in the retina and metabolic stress conditions in cultured neurons." (PMID 33915127, 2021).
diabetes (continued). "Type 1 diabetes mellitus (T1DM) is proposed to occur via autoimmune mechanisms targeting the pancreatic islet beta-cell, leading to reduced circulating insulin." (PMID 35098034, 2021). "Farris and colleagues, the first team to investigate diabetes-related endpoints in this mouse model, found that 6-month-old IDE-KO mice exhibited elevated fasting plasma glucose and insulin levels along with profound glucose intolerance." (PMID 33477364, 2021). "Type 2 diabetes mellitus (T2DM), a chronic metabolic disorder due to insulin resistance and insufficient insulin secretion, is becoming a major global public health issue." (PMID 33215869, 2021). "The participants with eGFR decline were older in age, had higher blood pressure, lower fasting insulin, and HOMA-IR, but a higher prevalence of diabetes, higher UACR, lower SCr, and higher eGFR at baseline than those without eGFR decline." (PMID 34918690, 2021). "This was later supported by the phenotype of greater glucose tolerance and insulin sensitivity in NLRP3-/- mice, which protect the mice from diet-induced obesity and diabetes." (PMID 34631209, 2021). "In the case of the characteristics of diabetes, people in FG VIM quartile 4 had a higher proportion of insulin users, individuals prescribed with ≥2 GLM during one year before baseline, and those with a duration of diabetes of at least five years." (PMID 34945244, 2021). "A previous study in insulin resistant subjects indicated that the proteome is sensitive to periods of weight gain and loss, however plasma protein changes during improvements in glucose control are not well studied, nor is the potential influence of diabetes medication on the proteome." (PMID 33279861, 2021). "Also, it appears to have a role in diabetes mellitus (DM) and blood glucose, as leptin analog decreases plasma glucose and plasma insulin increases insulin sensitivity." (PMID 35027962, 2021). "Repeated exercise bouts (exercise training) have been exhibited to elevate GLUT4 amount in populations with type 2 diabetes mellitus (T2DM) and metabolic syndrome (MetS), and these elevations are correlated with changes in serum insulin." (PMID 34159199, 2021). "Bezafibrate ameliorates diabetes and may benefit patients with nonalcoholic fatty liver disease and impaired glucose metabolism by reducing steatosis, enhancing hepatic mitochondrial mass, improving metabolic flexibility, and increasing hepatic insulin sensitivity." (PMID 34733160, 2021). "Thus, the mechanisms found here may be extrapolated to defective insulin secretion in diabetes." (PMID 33937248, 2021). "The metabolic interplay between insulin-dependent glucose metabolism and FAO are major areas of interest in diabetes research." (PMID 33466750, 2021). "The miR-375 and miR-148 play important roles in maintaining pancreatic cell mass, insulin biosynthesis, and normal glucose homeostasis, and here they were highly expressed in the pancreas under DFE administration compared with the diabetes group." (PMID 31790971, 2020). "People who suffer from type 1 diabetes mellitus (DM1) need to have their glycemic control 3 to 5 times a day and to take insulin up to 3 times a day." (PMID 33029335, 2020). "Compared with Non-CVD, patients with CVD were older and with longer duration of diabetes, SBP, lower LDL-C, lower HbA1c, lower insulin use, higher lipid lowering drugs use, higher antihypertensive drugs use, lower prevalence of DR." (PMID 33935960, 2020). "Type-2 diabetes mellitus (T2DM) is a complex disease characterized by diminishing pancreatic islet β-cell mass and impaired insulin release from these cells." (PMID 33195407, 2020). "•Data showing that hypoglycemic effects of verticinone are due to increased insulin secretion and glucose uptake and inhibition of carbohydrate-hydrolyzing enzymes may be of potential value for the scientists working on biological mechanisms of phytomedicine in diabetes mellitus." (PMID 31867414, 2020).
diabetes (continued). "LCCP app-based diabetes education is effective for glycemic control and improvement in SMBG behavior among patients with type 2 diabetes receiving insulin therapy." (PMID 32141838, 2020). "It is well accepted that the accumulation of visceral WAT belongs to the pathogenesis of insulin resistance and diabetes, while subcutaneous WAT is beneficial for insulin sensitivity and to maintain energy homeostasis." (PMID 33050029, 2020). "Type 2 diabetes mellitus (T2DM) is a chronic progressive disease characterized by insulin resistance and insufficient insulin secretion to maintain normoglycemia." (PMID 32131431, 2020). "Among those with previous diabetes treatment, most were receiving ‘OADs only’ treatment at SMH; more patients had initiated insulin treatment at LHLH." (PMID 32267843, 2020). "These three patients with diabetes (Cases 1, 6 and 10) were all admitted to the ICU and required increments in insulin rate due to resistant hypertriglyceridemia and persistent hyperglycemia, respectively." (PMID 33291273, 2020). "youth patients with FEP had higher cholesterol and LDLc than matched controls, while increased in insulin and HOMA-IR were found in early onset patients with dyslipidemia or family history of type 2 diabetes mellitus (T2DM)." (PMID 32848941, 2020). "Obese Zucker Diabetic Fatty (ZDF) rats that display all features of IR and metabolic syndrome (high glucose, insulin, triglycerides and fatty liver) had reduced PTEN expression (mRNA) (by around 40%) in the liver; the same was found in liver of obese humans." (PMID 32582754, 2020). "Type 2 diabetes mellitus (T2DM) is a long-term metabolic disorder which is characterized by high blood glucose in conditions of insulin resistance and/or insufficient insulin secretion." (PMID 32384902, 2020). "This is the prelude to type 2 diabetes mellitus (T2DM), a condition in which cells cannot respond properly to insulin." (PMID 32650579, 2020). "Regarding the blood parameters investigated, the levels of insulin and glycemia were higher in DIO rats compared to the controls, indicating a condition of insulin resistance typical of type 2 diabetes mellitus." (PMID 32120798, 2020). "Diabetes mellitus (DM) is a metabolic involving the interaction of genetic and environmental factors, and it is characterized by chronic hyperglycemia as the result of impaired insulin secretion, insulin resistance, or both." (PMID 32257538, 2020). "Once diabetes is detected, the ADA recommends that most adolescents with T1DM should initially follow a regimen of MDI of basal/bolus insulin." (PMID 32708413, 2020). "Specifically, for the insulin-sensitive Glut-4, an inverse regulation between UCP-2 and Glut-4 was reported several times in skeletal muscles that were impaired by diabetes." (PMID 32120777, 2020). "In STZ-induced animal model of diabetes, biosynthesized AgNPs and extract significantly improved SOD and CAT activity, decreased blood glucose, and enhanced plasma insulin level." (PMID 32478050, 2020). "Forty-five individuals with Type 1 diabetes mellitus (T1DM) and a history of insulin misuse completed an online questionnaire." (PMID 32967730, 2020). "Phoenix dactylifera extracts were administered to streptozotocin-induced type 2 diabetes mellitus (T2DM) rats (n = 50) daily for a month, and were found to significantly decrease (p < 0.001) glucose levels and increase insulin concentration." (PMID 33126433, 2020). "Major characteristics of type 2 diabetes mellitus (T2DM) are obesity, impaired insulin action, insulin secretory dysfunction and increased endogenous glucose output." (PMID 32503652, 2020). "The R2R+CBR algorithm has been implemented in the so-called Advanced Bolus Calculator for Diabetes (ABC4D), which is a novel BC for personalized insulin recommendations for people with T1D." (PMID 32664432, 2020).
diabetes (continued). "For example, a study of family behaviours and relationships to adherence and metabolic control, individuals with diabetes negative perceptions of support from family were associated with lower adherence to diabetes management areas (i.e. glucose testing, diet adherence, and insulin injections)." (PMID 32168342, 2020). "Cholecystectomy did not impair improvements of glycemic-related parameters, such as glucose, insulin and HbA1c, after RYGB, and patients achieved long-term diabetes remission." (PMID 32606360, 2020). "Type 2 diabetes mellitus (T2DM), one of the most common metabolic diseases, is characterized by insulin resistance and inadequate insulin secretion of β cells." (PMID 32960890, 2020). "In a subsequent study it was shown that bank voles had diabetes mellitus, accompanied with auto-antibodies to glutamic acid carboxylase (GAD65), tyrosine phosphatase-like protein IA-2, and insulin-resembling characteristic markers of human T1D." (PMID 32927606, 2020). "In the diabetic group, compared to the control group, higher levels of insulin and HOMA‐IR were observed after diabetes induction (p < .05)." (PMID 33278072, 2020). "DM type 1 or insulin-dependent diabetes mellitus (T1DM or IDDM) represents about 10% of the cases and results from the destruction of insulin-secreting pancreatic β-cells by an autoimmune-mediated process." (PMID 32041134, 2020). "Type 2 diabetes mellitus (T2DM) is characterized by a progressive deterioration of β-cell function and reduction in insulin sensitivity." (PMID 33015194, 2020). "Vitamin D and omega 3 co-supplementation improves fasting blood glucose, insulin and HDL-C levels and HOMA-B in reproductive-aged women with pre-diabetes and hypovitaminosis D and therefore can be recommended for glycemic control in these individuals." (PMID 32435279, 2020). "Finally, a possible role of resistin might be considered as a new link between obesity and diabetes, since resistin levels are increased in diet-induced obesity, as well as in genetic models of obesity and IR, and its inhibition enhanced insulin-stimulated glucose uptake." (PMID 33142938, 2020). "Compared with the non-CVD group, T2DM patients with CVD were more likely to be older and had longer duration of diabetes, higher SBP, lower HbA1c, and less likely to use insulin." (PMID 32431666, 2020). "Recently, we have shown that Ss infection has a protective role on diabetes-related parameters and that Ss infected T2DM individuals showed decreased levels of insulin and glucagon that increased following therapy." (PMID 33042134, 2020). "HD patients had significantly higher levels of serum insulin, higher levels of hs-CRP, and a significantly higher prevalence of diabetes mellitus relative to their control group counterparts (p < 0.05)." (PMID 32274214, 2020). "Notably, increased pancreatic CSE expression and H2S production in the Zucker diabetic fatty (ZDF) rat model of diabetes was shown to reduce circulating insulin levels, resulting in hyperglycemia that could be reversed by administration of PAG (see DL-Propargylglycine)." (PMID 33330130, 2020). "For instance, the hallmark “deregulated nutrient signalling” refers to pathways that sense and respond to nutrient availability such as “insulin and IGF1 signalling” (IIS) pathway, which is altered in diabetes." (PMID 32363781, 2020). "In pancreatic beta-cells, the expression of TXNIP is downregulated by insulin and is consistently increased in patients diagnosed with T2DM (type 2 diabetes mellitus)." (PMID 32973739, 2020). "With regard to diabetes, LPC 18:1 has been shown to be a novel ligand of GPR119, regulating pancreatic insulin secretion." (PMID 32093149, 2020). "Factors significantly associated with BI discontinuation were hospital level, patient recruitment setting, age, education level, out‐of‐pocket ratio, BMI, diabetes duration, self‐monitoring of blood glucose (SMBG), numbers of OADs, BI type and insulin regimen." (PMID 32318640, 2020).
diabetes (continued). "Patients with type 2 diabetes mellitus (DM) may exhibit impaired insulin secretion and insulin resistance." (PMID 32706828, 2020). "In the present study, the values of glycemia and insulin were higher in the DIO rats compared with the control CHOW rats, indicating a condition of insulin resistance typical of type-2 diabetes mellitus." (PMID 32375317, 2020). "Upregulation of PPARg expression/activity has been reported to improve insulin sensitivity and glucose uptake through GLUT 4 translocation pathway in human adipocytes and in animal models of diabetes." (PMID 32258479, 2020). "A similar finding was observed for stroke and MI, with exceptions in younger individuals and those with malignancy, shorter diabetes duration, baseline FG ≥ 126 mg/dL, T1DM, and treatment with thiazolidinedione and insulin." (PMID 32962711, 2020). "However, efforts to minimize the risk of exposure to COVID-19 have required social distancing and quarantine practices that may exacerbate insulin sensitivity through lower levels of physical activity, abrupt changes in social routine, poor dietary diversity, and diabetes distress." (PMID 32392473, 2020). "For type-1 diabetes mellitus (T1DM) subjects, their pancreatic β cells lose partial or whole function to produce insulin." (PMID 35415447, 2020). "C57BL/6J exhibit mild hyperglycemia and an increase in insulin level during 8–12 weeks of age, while C57BL/KsL show hyperglycemia, diabetes, and maximum weight at three to four months of age." (PMID 33322729, 2020). "Type 2 diabetes mellitus (T2DM) is a form of diabetes characterized by high blood glucose, insulin resistance, and a weaker insulin-stimulated response in the presence of high blood glucose level." (PMID 33013406, 2020). "Diabetes Mellitus (DM) is a metabolic disorder characterized by hyperglycemia as a consequence of defects in insulin secretion, in insulin’s mechanism of action or in both insulin’s secretion and action." (PMID 32424199, 2020). "The potential of salivary diagnostic for diabetes by IR spectroscopy using barium fluoride (BaF2) slides was suggested previously, however, the efficacy of DM monitoring in insulin-treated conditions using ultra-low volumes of saliva remains unknown." (PMID 32182246, 2020). "Diabetes mellitus in CHC patients is frequently ascribed to a correlation between increased serum and hepatic iron stores and insulin resistance or direct damage to the pancreatic β cells." (PMID 33520544, 2020). "Since GLP-1 production is assumed to remain intact in well-controlled diabetic patients and stimulates insulin release and lowers postprandial glycemia, several therapeutic approaches are being developed to increase GLP-1 action for treating diabetes mellitus." (PMID 32983244, 2020). "Another study, however, indicated that 4 weeks of STZ-induced diabetes did not reduce the cross-sectional area of lower lumbar MNs other than that of the bulbocavernosus MNs, which were associated with low levels of testosterone and were prevented by the administration of insulin." (PMID 33050583, 2020). "Even after controlling for age, years since diabetes diagnosis, number of comorbidities, number of diabetic complications, insulin use and depressive symptoms, Poor sleep quality in people with T2DM still significantly reduce diabetes-related quality of life." (PMID 32448338, 2020). "LCCP app-based diabetes education is effective for glycemic control and SMBG behavior improvement in patients with type 2 diabetes receiving insulin therapy." (PMID 32141838, 2020). "In what concerns to diabetes treatment at the last evaluation, in our sample all T1DM patients were under insulin therapy, mainly basal-bolus regimen." (PMID 33292447, 2020). "A 40-year-old man with brittle diabetes, who was included in the TRIMECO trial, became insulin-independent 2 months after pancreatic islet transplantation." (PMID 32950058, 2020).